MSTN (myostatin)
Diseases named in the same sentence as MSTN in open-access papers (continued):
Sharing a sentence is not in itself a finding about the gene and the disease.
sarcopenia (continued). "Osteoporosis and sarcopenia may share several pathophysiological mechanisms, including myostatin, Wnt-β-catenin signal pathway regulation, deficiencies in certain nutrients such as vitamin D, and inflammatory cytokine activity." (PMID 40994955, 2025). "The authors explain that this association between myostatin levels and prognosis may be linked with sarcopenia, frailty, and poor nutritional status." (PMID 40292469, 2025). "Other benefits from resistance exercises may include the reduction of myostatin and modulating the activity of NF-kB, further reducing muscle loss and dysfunction associated with sarcopenia." (PMID 38919474, 2024). "Heart disease may cause sarcopenia through common pathogenetic pathways, including inflammation, insulin-like growth factor-1, angiotensin, sex hormones, myostatin, physical inactivity, low EF, and malnutrition." (PMID 38737730, 2024). "However, in this study, myostatin levels were significantly higher in the sarcopenia group, while in our study myostatin concentration was inversely associated with sarcopenia." (PMID 39125361, 2024). "In advanced sarcopenia, where there is a significant loss of muscle mass, there may be a decrease in myostatin levels due to diminished production by the low muscle tissue." (PMID 39125361, 2024). "Even though the exact underlying physiological mechanisms of sarcopenia are largely unknown, the activin/myostatin pathway appears to have a central role in the regulation of muscular growth and atrophy." (PMID 39251484, 2024). "In particular, the inhibition of satellite cell proliferation and differentiation and muscle fiber protein synthesis occurs in the presence of myostatin, and increased levels of myostatin are significantly associated with SkM-wasting diseases, such as cancer cachexia and sarcopenia." (PMID 39594525, 2024). "Moreover, it has been reported that leptin can increase muscle mass by reducing the expression of atrophy-associated factors, including MuRF1, myostatin, and MAFbx, in muscles, indicating that leptin is significantly related to sarcopenia severity and risk." (PMID 37153220, 2023). "Muscle loss in primary and secondary sarcopenia appears to be driven by different mechanisms: sarcopenia in the elderly is primarily produced by anabolic resistance induced by myostatin; meanwhile, secondary sarcopenia appears to be driven by catabolic processes." (PMID 37771723, 2023). "Finally, increased myostatin levels, a protein that inhibits muscle growth, have been implicated in the development of sarcopenia." (PMID 36984525, 2023). "Myostatin was reported to be associated with sarcopenia in community-dwelling older adults." (PMID 36330524, 2022). "Myostatin is negatively associated with satellite cell activation and age-related muscle loss, with higher serum myostatin concentrations being associated with increased odds of sarcopenia in men." (PMID 40479264, 2022). "Myostatin is a mediator of sarcopenia and is associated with insulin resistance." (PMID 35287731, 2022). "Moreover, myostatin changes are also dependent on age and comorbidities, thus claiming for further studies that define better the specific association between the levels of myostatin and frailty/sarcopenia-parameters." (PMID 36556504, 2022). "Furthermore, myostatin inhibition has been studied in various forms of sarcopenia associated with chronic kidney disease and other chronic illnesses." (PMID 36012334, 2022). "The study can assist in developing therapeutic strategies to treat DMD, and the application of BLS-22 may be extended to various forms of sarcopenia associated with chronic kidney disease and other chronic illnesses associated with myostatin inhibition." (PMID 36012334, 2022). "Increased levels of serum total IS might play a role in sarcopenia, while increased levels of serum myostatin are associated with muscle mass in patients with CKD." (PMID 36287929, 2022).
sarcopenia (continued). "Elevated TNF-α in turn stimulates the expression of myostatin, which can cause muscle atrophy by activating proteasome-mediated intracellular protein catabolism, suggesting that inhibiting myostatin-triggered ROS can reduce muscle wasting associated with sarcopenia." (PMID 35004684, 2021). "The age-related pathogenesis of sarcopenia is complex and may involve interactions of genetic predisposition with changes in hormone, inflammatory markers, and myostatin expression." (PMID 34782685, 2021). "Likewise, sarcopenia associated with aging causes an increase in the expression of myostatin, a protein that inhibits the progression of the cell cycle and regulates the levels of factors that control muscle growth." (PMID 34067004, 2021). "Possibly, myostatin inhibition may be a therapeutic target for muscle mass loss disorders, such as atrophy, sarcopenia, and cancer." (PMID 33807959, 2021). "In other words, myostatin expression could be one treatment target to prevent sarcopenia and hepatic fibrosis, thereby lowering the risk of hepatic decompensation and HCC development." (PMID 33198216, 2020). "Background and Aim: Previous studies reported that serum myostatin is associated with sarcopenia." (PMID 33198216, 2020). "The interactions between sarcopenia, muscle dysfunction, and myostatin and how they can affect HCC risk in cirrhotic patients are unknown." (PMID 33198216, 2020). "Elevated levels of ammonia may lead to sarcopenia, or muscle wasting, and this has been linked to increased myostatin expression, a negative regulator of muscle growth." (PMID 32629824, 2020). "The overexpression of myostatin can cause muscle atrophy and plays an important role in sarcopenia." (PMID 32082422, 2020). "For MSTN, some studies found a differential expression in cases versus healthy controls irrespective of the presence of sarcopenia or weight loss whereas others indicated decreased expression only for those cases in which sarcopenia was present." (PMID 31498843, 2019). "Hyperammonemia caused by advanced LC status can lead to hypermyostatinemia (myostatin is a negative regulator of muscle mass synthesis), and subsequent serious complications including sarcopenia, which may be linked to adverse outcomes." (PMID 31766742, 2019). "Therefore, myostatin has attracted attention as a molecular target for suppressing the loss of muscle weight associated with aging and sarcopenia." (PMID 30805562, 2019). "Serum myostatin levels (confidence interval [CI] of OR = 1.02–1.23, p = 0.019) and the male gender (CI of OR = 1.60–84.61, p = 0.015) were associated with an increased likelihood of pre-sarcopenia by hSMI." (PMID 26785759, 2016). "Recent surveys indicate that polymorphisms in genes controlling muscle mass in humans and mammals, including the genes encoding insulin growth factor 1 (IGF1), myostatin, follistatin and components of the activin receptor protein complex, are linked to increased risk of sarcopenia." (PMID 24092876, 2013). "Besides its function in reducing sarcopenia, it appears that myostatin also regulates the structure and function of tendon tissues, as the stiffness of tendons is 14 times higher in myostatin-deficient mice than in their wild type controls." (PMID 21283721, 2011). "For example, elevated myostatin expression correlates with several settings of muscle loss including prolonged bed rest in young men, chronic disuse atrophy in older patients and age-related muscle wasting (sarcopenia)." (PMID 19412331, 2007). "Therefore, we aimed to examine whether circulating ApoJ and MSTN levels are associated with sarcopenia in older adults, focusing on key diagnostic domains such as muscle mass, handgrip strength, and physical performance (PP)." (PMID 40661742, 2025). "It is hypothesized that MSTN level increases with age and loss of skeletal muscle, and a serum MSTN increase of 1 ng/mL is associated with an 11% increase in the odds of developing sarcopenia in older men." (PMID 40801027, 2025).
sarcopenia (continued). "Accordingly, myostatin inhibitors, including antibody, recombinant protein, and peptide, have been shown to be useful tools for inducing muscle growth, leading to the promising treatment of muscle atrophic disorders, such as muscular dystrophy, sarcopenia, and cancer-associated cachexia." (PMID 36986496, 2023). "Therefore, preclinical studies on the use of anti-MSTN antibodies in model animals subjected to limb unloading will be needed to confirm and validate the efficacy of this treatment in counteracting the loss of muscle mass typical of sarcopenia." (PMID 35185612, 2022). "However, the variable results concerning serum and muscle myostatin levels and loss of muscle mass in humans apparently rule out a major role for this signaling pathway, despite the evidence of sarcopenia decrease following myostatin inhibition in animal investigations." (PMID 33401549, 2021). "In one study, plasma myostatin concentration in three groups of subjects (19–35, 60–75, and 76–92 years) were highest in the 76–92-year-old group, which suggests that plasma myostatin could be used as a biomarker for diagnosing age-associated sarcopenia." (PMID 33019579, 2020). "Owing to the potent inhibitory role of MSTN on muscle growth, there has been much interest in MSTN-blocking as a strategy to treat muscle atrophy caused by chronic diseases such as cancer, kidney failure, obstructive pulmonary disease, cardiomyopathy, liver cirrhosis, and age-associated sarcopenia." (PMID 30998775, 2019). "The inhibition of myostatin signalling by anti‐myostatin antibodies or activin receptor inhibitors seems to be a great challenge to increase muscle mass in case of muscle wasting diseases, for example cancer‐associated cachexia, age‐related sarcopenia or plaster cast immobilization." (PMID 30129974, 2018). "The prevalence of sarcopenia is higher in women than men; however, we can only speculate that myostatin plays a causal role in age-associated muscle loss in women and that women may be more responsive than men to anti-myostatin therapies." (PMID 26180626, 2015). "Although clinical trials targeting sarcopenia and muscle defects using anti-myostatin antibodies, stem cell-derived products, and acellular scaffolds have reported modest gains in strength and lean mass, no definitive regenerative therapy has been approved." (PMID 42278293, 2026). "Myostatin, the first recognized myokine, is an important negative regulator of muscle mass, and isassociated with sarcopenia; it also appears to have a role in glucose homeostasis,increasing insulin resistance." (PMID 41585414, 2025). "Changes in myostatin, IGF-1, follistatin, and creatine kinase levels have been shown to be linked with COVID-19-related sarcopenia." (PMID 40943488, 2025). "This study therefore investigates serum myostatin and irisin levels in RA patients, analyzing their clinical correlations with sarcopenia and OP, particularly OPF, to identify potential biomarkers and therapeutic targets for future research." (PMID 40593203, 2025). "In contrast, MSTN levels were lower in individuals with reduced HS, impaired PP, or severe sarcopenia." (PMID 40661742, 2025). "In recent years, novel therapeutic interventions, such as vitamin D, angiotensin receptor blockers, inhibitors of myostatin, and anabolic steroids, have been proposed for counteracting sarcopenia in patients undergoing dialysis." (PMID 40142260, 2025). "In contrast, the Low ApoJ/High MSTN group had a prevalence of 0% for both sarcopenia or severe sarcopenia, suggesting a potential protective effect of high MSTN and low ApoJ levels against sarcopenia." (PMID 40661742, 2025). "This study aimed to examine the association of biomarkers recommended by the ESCEO guidelines—including adiponectin, myostatin, P3NP, CRP and TNF‐α—with sarcopenia diagnostic criteria using plasma‐derived EV markers in a prospective cohort." (PMID 40162588, 2025).
sarcopenia (continued). "It suggests that in men, sarcopenia is more influenced by myostatin and serum triglycerides, whereas in women, it is driven by anabolic decline, particularly reduced IGF-1 levels, and nutrition." (PMID 40284239, 2025). "Subgroup analyses revealed that RA patients with sarcopenia had higher myostatin (P = 0.002) and lower irisin (P = 0.003) than RA patients without sarcopenia." (PMID 40593203, 2025). "Several studies have linked sarcopenia in CKD to uremic conditions and molecular mechanisms such as caspase activation, myostatin signaling, and the dysregulation of specific miRNAs." (PMID 41369335, 2025). "Future research should compare these indices with other emerging sarcopenia biomarkers (e.g., myostatin, IL-6), or consider combining them into composite indices." (PMID 40712242, 2025). "Specifically, the normal group had a myostatin level of 15.14 ± 11.79 pg/mL, whereas the sarcopenia group had 22.42 ± 29.31 pg/mL (p = 0.153)." (PMID 40162588, 2025). "Myostatin and irisin, the key regulators of muscle metabolism, are myokines secreted by skeletal muscles that significantly influence osteoporosis (OP) and sarcopenia." (PMID 40593203, 2025). "Myostatin inhibitors have therefore been explored as therapeutic agents for sarcopenia, a condition marked by reduced muscle mass, strength, and physical function." (PMID 40868997, 2025). "Current therapeutic paradigms overwhelmingly focus on continuous MSTN repression for muscle‐wasting conditions (muscular dystrophies, cachexia, sarcopenia) [s13], yet completely overlook circadian dynamics." (PMID 41287261, 2025). "Studies to date have explored the relationship between Single Nucleotide Polymorphisms (SNPs) and sarcopenia, focusing on vitamin D receptor (VDR), interleukin-6 (IL6), alpha-actinin-3 (ACTN3), and Myostatin (MSTN) polymorphisms." (PMID 40772803, 2025). "Previous studies have associated polymorphisms with sarcopenia (ACTN3; MTHFR; NRF2), muscle hypertrophy (TGFβ; Myostatin, GDF-8) and response to ST (ACTN3, ACE, NOS3, PPARGC1A/B, VEGFA)." (PMID 40648598, 2025). "Myostatin promotes muscle degradation by inhibiting satellite cell activation and muscle regeneration, contributing to sarcopenia." (PMID 41515940, 2025). "Various pharmaceutical strategies aimed at addressing primary sarcopenia have been explored, including selective androgen receptor modulators and the inhibition of activin receptors or myostatin through monoclonal antibodies." (PMID 40282842, 2025). "bimagrumab treatment, a monoclonal antibody that blocks activin type II receptor (ActRII) to inhibit myostatin signaling and stimulate protein anabolism was added to optimized standard of care in community‐dwelling older adults with sarcopenia." (PMID 39601205, 2025). "It was found that resistance training plus epicatechin (a polyphenol) for 8 weeks reduced myostatin levels by 49% compared to resistance training alone in older people with sarcopenia." (PMID 39997712, 2025). "In contrast, Myostatin levels were negatively correlated with muscle mass, and Myostatin levels were 2.3-fold higher in elderly patients with sarcopenia." (PMID 41209336, 2025). "Studies have also demonstrated that BFRT can reduce myostatin expression, thereby positively impacting the improvement of sarcopenia." (PMID 40926887, 2025). "For instance, patients with sarcopenia exhibit significantly elevated myostatin levels alongside reduced Akt phosphorylation efficiency." (PMID 40926887, 2025). "We comprehensively assessed sarcopenia in older adults by evaluating muscle mass, muscle strength, and PP, while simultaneously measuring circulating levels of ApoJ and MSTN, which are representative hepatokines and myokines, respectively." (PMID 40661742, 2025). "In conclusion, myostatin and irisin are significantly correlated with sarcopenia and OPF in RA patients." (PMID 40593203, 2025).
sarcopenia (continued). "The dual evaluation of muscle mass restoration and molecular markers offers robust evidence supporting the therapeutic potential of MSTN-ASO in uremic sarcopenia." (PMID 40243849, 2025). "Myostatin levels predicted sarcopenia in KTRs (cut-off: 390 pg/mL) and inversely correlated with Metabolic equivalent of Tasks (METs), handgrip strength (HGS), and graft performance." (PMID 41464844, 2025). "Myopathy and sarcopenia both trigger myostatin overexpression, leading to a strong activation of the Smad2/3 path, which increases proteasomal and autophagic-lysosomal capabilities." (PMID 40943120, 2025). "Elevated myostatin is linked to muscle wasting, frailty, and conditions such as obesity, COPD, sepsis, and sarcopenia and is considered a potential biomarker for muscle impairment and rehabilitation needs." (PMID 40943488, 2025). "Understanding the dual role of myostatin in both healthy and pathological states not only provides potential targets for the treatment of sarcopenia but also lays the foundation for developing personalized intervention strategies." (PMID 41140691, 2025). "Although only six KTRs were sarcopenic, myostatin independently predicted sarcopenia (OR 1.002, 95% CI: 1.001–1.005, p = 0.04)." (PMID 41464844, 2025). "Myostatin is a key pathway involved in muscle atrophy, particularly in certain cachexia models and sarcopenia." (PMID 39764565, 2025). "Dysregulation of the gut microbiota can also contribute to the development or progression of sarcopenia and obesity by altering the expression of myostatin and atrogin-1, as well as disrupting the signaling between the enteric nervous system and the brain." (PMID 41373947, 2025). "The inhibition of the myostatin pathway is emerging as a novel and compelling therapeutic target for managing sarcopenia." (PMID 40142260, 2025). "Further studies are needed to explore the relationship between myostatin, cachexia, sarcopenia and aging, excluding other factors influenced by aging." (PMID 39764565, 2025). "Recent studies have identified a causal relationship between sarcopenia and increasing risk of HCC in European populations, implying that MSTN, the primary mediator of sarcopenia, is a promising biomarker candidate for HCC risk stratification." (PMID 40269686, 2025). "For instance, in a large human observational study involving 463 community-dwelling adults aged 53–92 years in Taiwan, serum myostatin, muscle mass, strength, and function were measured according to Asian Working Group for Sarcopenia (AWGS) criteria." (PMID 40944148, 2025). "Therapeutic approaches to sarcopenia, highlighting advancements in muscle mass interventions, include 20‐hydroxyecdysone (20E) and anabolic agents like testosterone and myostatin inhibitors." (PMID 40485364, 2025). "Given the significant role of myostatin in sarcopenia with ethanol, the mechanistic link between HIF1α and myostatin needs to be evaluated." (PMID 40308032, 2025). "MSTN inhibition is promising as a sarcopenia treatment, with the potential to improve SM performance." (PMID 41011274, 2025). "Reduced gut microbiota quantity and variety enhances intestinal permeability, which raises muscle MSTN levels via the gut–muscle axis, leading to sarcopenia." (PMID 41011274, 2025). "In advanced chronic liver disease patients, sarcopenia is primarily exacerbated by the upregulation of myostatin due to hyperammonaemia." (PMID 39796612, 2025). "Comparison of sarcopenia related factors between low and high groups based on myostatin, P3NP and TNF‐α cutoff values." (PMID 40162588, 2025). "Genetic polymorphisms in key pathways involved in muscle regulation, such as the activin/myostatin signaling pathway, are thought to contribute to the development of sarcopenia." (PMID 40428823, 2025). "Multiple logistic regression analyses were conducted to determine the impact of various factors, including ApoJ and MSTN levels, on the ORs for sarcopenia and severe sarcopenia." (PMID 40661742, 2025).